MYLK4 (myosin light chain kinase family member 4)
Synonyms: SgK085; MLCK4
Tractability: Small molecule: a structure with a bound ligand is known; a high-quality ligand is known; it belongs to a druggable protein family. PROTAC: a small molecule that binds it is known.
Target class: Kinase; CAMK protein kinase MLCK family; CAMK protein kinase group; Enzyme; Protein Kinase
Chemical probes: SGC-PI5P4Kγ/MYLK4-1 (high quality)
Gene: Protein-coding gene on chromosome 6 (2,663,629 to 2,770,330, reverse strand). Ensembl gene ENSG00000145949.
Subcellular location (Human Protein Atlas): Golgi apparatus; Nucleoli; Vesicles
Gene Ontology:
Molecular function: protein binding; myosin light chain kinase activity; ATP binding; protein kinase activity; protein serine kinase activity; protein serine/threonine kinase activity
Biological process: signal transduction
Cellular component: cytoplasm
Genetic constraint (gnomAD): Loss-of-function variants: 41 observed, 45.94 expected, observed/expected ratio (o/e) 0.89, 90% interval 0.69 to 1.16. The upper end of that interval is the gene's LOEUF score, 1.16, which puts it in group 5 of 6, group 1 being the genes least tolerant of losing a copy. Missense variants: 435 observed, 480.92 expected, observed/expected ratio (o/e) 0.9, 90% interval 0.83 to 0.98. Synonymous variants: 165 observed, 181.62 expected, observed/expected ratio (o/e) 0.91, 90% interval 0.8 to 1.03.
Homologues: Orthologues: chimpanzee MYLK4 (99% identical), macaque MYLK4 (95% identical), dog MYLK4 (89% identical), mouse Mylk4 (85% identical), guinea pig MYLK4 (84% identical), rat Mylk4 (71% identical), tropical clawed frog mylk4 (61% identical), zebrafish mylk4b (58% identical), zebrafish mylk4a (43% identical). Paralogues in human: MYLK3 (56% identical), MYLK2 (48% identical), PSKH1 (28% identical), DCLK2 (27% identical), CAMK1D (27% identical), DCLK1 (27% identical), DCLK3 (26% identical), PSKH2 (26% identical), CAMK2D (26% identical), CAMK1 (26% identical), CAMK1G (25% identical), CAMK2A (25% identical), and 10 more.
Diseases named in the same sentence as MYLK4 in open-access papers:
MYLK4 is named in the same sentence as 14 diseases in open-access papers, as found by Europe PMC text mining. Sharing a sentence is not in itself a finding about the gene and the disease. The quoted sentences say what the papers report.
cardiomyopathy (2 papers, 2016 to 2017). A disease of the heart muscle or myocardium proper. "A small number of other genes were regulated inversely in different adult forms of cardiomyopathy (RCM/DCM or RCM/ICM datasets) relative to RCM, including intelectin 1 (ITLN1), delta-like 1 homolog (DLK1), reelin (RELN), and myosin light chain kinase family, member 4 (MYLK4)." (PMID 28098235, 2017).
osteosarcoma (2 papers, 2021 to 2025). A usually aggressive malignant bone-forming mesenchymal neoplasm, predominantly affecting adolescents and young adults. "MYLK4 accelerates tumour progression through activation of epidermal growth factor receptor signalling in osteosarcoma." (PMID 40463716, 2025). "Mechanistically, mass spectrum analysis showed that MYLK4 interacted with the epidermal growth factor receptor (EGFR) in osteosarcoma cells and promoted growth and metastasis via the EGFR signaling pathway." (PMID 33980265, 2021). "According to the result of animal experiment, we also found MYLK4-knockdown orthotopic osteosarcoma implanted mice not only had the reduced lung metastasis, but also had the smaller tumor weight." (PMID 33980265, 2021). "We investigated the expression of myosin light chain kinase family members between metastasis and non-metastasis patients in the TARGET database and ensured that only myosin light chain kinase family member 4 (MYLK4) had higher expression in metastatic osteosarcoma patients." (PMID 33980265, 2021). "Since MYLK4 promotes the OS progress via the EGFR signal pathway, we attempt to combine the MYLK4 inhibitor with the EGFR inhibitor in order to see whether this combination synergistically inhibits the growth and metastasis of osteosarcoma in vitro and in vivo." (PMID 33980265, 2021).
and acute leukemia (1 paper, 2013). "Among these overlapped regions, several functional genes were found, including LIM and senescent cell antigen-like domains 1 (LIMS1), myosin light chain kinase family, member 4 (MYLK4), frizzled family receptor 6 (FZD6), and brain and acute leukemia, cytoplasmic (BAALC)." (PMID 23390598, 2013).
emphysema (1 paper, 2023). "Adrenomedullin and myosin light chain kinase family member 4 (MYLK4) act against emphysema." (PMID 38203236, 2023).
heart failure (1 paper, 2024). Inability of the heart to pump blood at an adequate rate to meet tissue metabolic requirements. "Mylk4 is an integral component of the focal adhesion pathway involved in protein phosphorylation, with a key role in the altered cytoskeletal network of cardiomyocytes in heart failure and malignant cell proliferation." (PMID 38558813, 2024).
ischemic cardiomyopathy (1 paper, 2025). Ischemic cardiomyopathy is a cardiomyopathy in which a weakness in the muscle of the heart due to inadequate oxygen delivery to the myocardium with coronary artery disease being the most common cause. "Mylk4, a cardiomyocyte cytoskeletal gene, was downregulated in the transverse muscle of the tongue from 4NQO-induced mice compared to normal mice, consistent with previous findings in tissue samples from ischemic cardiomyopathy." (PMID 40678065, 2025).
optic neuritis (1 paper, 2025). Optic neuritis is inflammation of the optic nerve, the nerve that carries the visual signal from the eye to the brain.The conditionmay cause sudden, reduced vision in the affected eye(s). "We established an improved experimental model of NMOSD optic neuritis and found that targeting ROCK/MYLK4 signaling confers significant neuroprotection." (PMID 41227356, 2025). "Thus, we hypothesized that dual ROCK/MYLK4 blockade with ITRI-ES would provide superior neuroprotection in NMOSD-related optic neuritis by simultaneously suppressing converging mechanisms of barrier breakdown and immune activation, beyond what single-pathway inhibition could achieve." (PMID 41227356, 2025). "Thus, dual ROCK/MYLK4 inhibition may simultaneously target multiple cell types—neurons, endothelial cells, microglia/macrophages, and astrocytes—providing a comprehensive therapeutic approach in NMOSD optic neuritis." (PMID 41227356, 2025).
tumor (3 papers, 2021 to 2025). "Although the genes in (PRKAA2, GNG7, MYL3, NOS1, ADCY1, PLCB1, MYLK3, and MYLK4) the apelin/APJ signaling axis are found to be downregulated and might not be considered responsible in cdRCC progression, downregulation of GNG7 tells a different story due to its tumor‐suppressive activity." (PMID 40304310, 2025).
infection (1 paper, 2025). The state of being infected such as from the introduction of a foreign agent such as serum, vaccine, antigenic substance or organism. "In contrast, MYLK4 (HSC-niche) and ARNTL (platelet production) expression by MK did not change after infection." (PMID 41296814, 2025).
MYLK4 also shares sentences with these, for which no sentence is quoted: cancer (1 paper); dilated cardiomyopathy (1); glaucoma (1); malaria (1); myopathies (1).